NOTCH1 (notch receptor 1)
Diseases named in the same sentence as NOTCH1 in open-access papers (continued):
Sharing a sentence is not in itself a finding about the gene and the disease.
renal fibrosis (20 papers, 2012 to 2025). A final common manifestation of a wide variety of chronic kidney diseases characterized by glomerulosclerosis and tubulointerstitial fibrosis. "While studies have linked Ccn3 to integrin and Notch1 mediated signaling and prevention of renal fibrosis, the role of Ccn3 in the heart post injury is virtually unexplored." (PMID 36998974, 2023). "Elevated NOTCH1 has been found to stimulate renal fibrosis, while loss of NOTCH1 activity has decreased pulmonary fibrosis." (PMID 36612107, 2022). "In summary, this study first confirmed that low dose of BV could cause obvious EMT-related renal fibrosis in vivo and in vitro, which was associated with the activation of the TGFβ1/Smad3 and Notch1/NICD signaling pathway." (PMID 35873571, 2022). "Hence, we further demonstrated that BV treatment could promote EMT and fibroblast-like properties’ acquisition in renal tubular epithelial cells through TGFβ1 and Notch1-mediated fibrotic signaling responses, all of which eventually caused renal fibrosis." (PMID 35873571, 2022). "Silencing PLK2 significantly inhibited the activation of the Notch1 signaling pathway and reduced the expression of renal fibrosis-related markers, while overexpression of HES1 rescued the downregulation of markers induced by si-PLK2." (PMID 40822939, 2025). "The overexpression of active Notch1 in tubular epithelial cells aggravated renal fibrosis, while the inhibition of Notch resulted in the amelioration of renal fibrosis." (PMID 40563434, 2025). "Notch 1 and Notch 3 ligand are two major receptors involved in renal fibrosis; Jagged-1 is the most studied ligand of Notch signaling." (PMID 33456568, 2021). "Induction of renal fibrosis has previously been demonstrated to be dependent upon Jag1/Notch1 signalling." (PMID 31570767, 2019). "Indeed, overexpression of the intracellular domain of Notch1 in tubular epithelial cells is sufficient to induce aggressive renal fibrosis in mouse models." (PMID 31570767, 2019). "Our findings suggest that the activation of epithelial and interstitial Notch1 signalling following injury contributes to the myofibroblastic phenotype and renal fibrosis through the EMT in TECs and to the FMD in fibroblasts by targeting downstream TGF-β1/Smad2/3 signalling." (PMID 31718671, 2019). "It is therefore possible that activation of Notch receptors, especially for Notch-1 and Notch-2, in the development and progression of renal fibrosis could be in a context-dependent, cell-type-specific manner." (PMID 29101337, 2017). "Increased Notch activity due to enhanced Jagged-1 ligand and Notch1 expression has also been detected in fibrotic kidneys and therefore may be relevant to the pathogenesis of renal fibrosis." (PMID 22363487, 2012). "Additionally, berberine synergistically reduces renal fibrosis by suppressing the Notch/Snail pathway (downregulating Jagged1, Notch1, and Snail1) and the RhoA/ROCK pathway (reducing FN accumulation), as well as blocking the SphK1- S1P signaling cascade (decreasing S1P2 receptor expression)." (PMID 40567371, 2025). "Thus, it was suggested that tanshinone IIA may exert a beneficial role in improving renal fibrosis by upregulating the expression of miR‐34a‐5p and directly targeting Notch1." (PMID 36348805, 2022). "However, to date, the relationship and underling mechanism between IL-22 and Notch1 signaling pathway, and the exact role of IL-22 signaling pathway in the progression of renal fibrosis are not elucidated." (PMID 32338120, 2020). "Thus, Notch1 signalling plays a crucial role in the development of renal fibrosis." (PMID 31718671, 2019). "Therefore, epithelial and interstitial Notch1 signalling may contribute to renal fibrosis via the induction of EMT/FMD, and inhibition of Notch1 signalling may have a therapeutic role for fibrotic kidney diseases." (PMID 31718671, 2019).
renal fibrosis (continued). "This study evaluated the effects of CA on renal fibrosis, lipid deposition and lipid metabolism by constructing in vitro and in vivo models of DKD, and detected the improvement of Notch1 and Stat3 signaling pathways." (PMID 38952291, 2024). "Notch1 activation of the AKT/mTOR pathway subsequently suppressed autophagy, leading to the occurrence and development of renal fibrosis." (PMID 36348805, 2022). "Blockade of Notch1 signalling with DAPT can inhibit and even reverse to some extent the EMT and FMD programmes, reducing myofibroblastic phenotype and attenuating renal fibrosis." (PMID 31718671, 2019). "Among these known miR-34a target genes, Notch1 and Jagged1 were shown to promote EMT and renal fibrosis in tubular epithelial cells by activation of the Notch signaling pathway." (PMID 22363487, 2012).
T-cell lymphoma (20 papers, 2009 to 2025). "Mutations in NOTCH1 have been found with high frequency in all major oncogenic subclasses of human T cell lymphomas, suggesting NOTCH1 plays a significant role in lymphomagenesis." (PMID 25759795, 2015). "In a small study, half of the T cell lymphomas examined carried activating NOTCH1 mutations and/or mutations in the NOTCH-inhibiting FBXW7, which encodes an ubiquitin ligase that degrades NOTCH." (PMID 25759795, 2015). "On the other hand, missense or frame-shift mutations in the PEST domain, more commonly found in mouse T cell lymphomas, stabilize Notch1 proteins by preventing ubiquitin-mediated degradation." (PMID 22393458, 2012). "Although E proteins have been shown to be involved in the transcriptional activation of the Notch1 gene, the situations in T cell lymphomas resulted from E protein deficiency may be entirely different." (PMID 22393458, 2012). "The ZMYM2–FGFR1 fusion gene has been reported to drive the development and progression of T-cell lymphoma through sustained activation of the Notch1 signaling pathway." (PMID 41306918, 2025). "RT-qPCR on T-cell and non-T-cell lymphoma samples showed that Notch1 mRNA levels were upregulated, concomitant with the idea that Notch1 was being transcriptionally dysregulated in the malignant T-cells." (PMID 37160922, 2023). "In several mouse models of T-cell lymphoma, Dlx5 has been shown to act as an oncogene by cooperating with activated Akt, Notch1/3, and/or Wnt to drive tumor formation." (PMID 34203994, 2021). "Here, we made use of our collections of T cell lymphomas developed in mice expressing Id1 or Notch1 intracellular domain (N1C)." (PMID 22393458, 2012). "To test if these events occurred in Id1 transgenic T cell lymphomas, we determined levels of Notch1 transcripts by using PCR primers specific for exons 5–6 and exons 33–34 to amplify Notch1 transcripts via the 5′ and 3′ ends, respectively." (PMID 22393458, 2012). "The T-cell lymphomas overexpress Notch1 and the mechanism behind this appears to be multifactorial." (PMID 37160922, 2023). "Therefore, we purified Notch1/CSL-dependent complexes from nuclear extracts prepared from a Notch-driven T-cell lymphoma cell line (4084)." (PMID 34551776, 2021). "In addition, Lef1 has been reported as a transcriptional target of NOTCH1 in T-cell lymphomas and to accelerate Notch1-induced lymphomagenesis in mice." (PMID 31586130, 2020). "In this paper, western blotting exhibited that ITK inhibitor could also downregulate the activity of Notch1 level in malignant T-cell lymphoma cell lines." (PMID 30814910, 2019). "Evidence for aberrant V(D)J rearrangements in 73-deficient thymocytes was obtained by assaying for internal deletion at the Bcl11b and Notch1 loci, which both contain cryptic recombination signal sequences (RSS) that are accessible to Rag, and are frequently mutated in T cell lymphomas." (PMID 19907659, 2009). "Towards this end a panel of T-cell acute lymphoblastic leukaemia (T-ALL) cells obtained from NOTCH1-driven mouse models and EL4 T-cell lymphoma cells were subjected to treatment with CMA18." (PMID 28874664, 2017). "Interestingly, the T-cell lymphomas had expression of Notch1 and Hes1 similar to the DN3 stage rather than the DN4 stage." (PMID 37160922, 2023).
Alzheimer disease (19 papers, 2008 to 2026). A progressive, neurodegenerative disease characterized by loss of function and death of nerve cells in several areas of the brain leading to loss of cognitive function such as memory and language. "DNER is highly expressed in substantia nigra and is an activator of the NOTCH1 pathway which has been implicated in the aetiology of other neurodegenerative disorders including Alzheimer’s disease." (PMID 30867224, 2019). "The use of GSIs that were originally developed for Alzheimer’s disease and cancer is primarily based on the premise that GSIs act by inhibiting the cleavage of GS on Notch ligands, thereby resulting in Notch 1 signaling blockade." (PMID 35973981, 2022). "It was found that in Alzheimer disease, hydrogen peroxide induced the up-regulation of Notch-1 possibly due to the activation of enzymes involved in Notch-1 cleavage and gamma-secretase activation." (PMID 33381027, 2020). "Notch signaling plays an instrumental role in hippocampus-dependent memory formation and recent evidence indicates a displacement of Notch1 and a reduction its activity in hippocampal and cortical neurons from Alzheimer's disease (AD) patients." (PMID 28848392, 2017). "Notch1 inhibitors such as γ-secretase are potential therapeutic agents for treatment of tumor, Alzheimer’s disease and cardiovascular diseases." (PMID 24358274, 2013). "Increased Notch-1 expression has also been observed in the hippocampus from patients with Alzheimer’s disease and fronto-temporal lobe dementia or Pick’s disease, where abnormal tau aggregates are present." (PMID 22952817, 2012). "Moreover, Notch1 imbalances have been reported in patients affected by Alzheimer’s disease, fronto-temporal dementia and Down’s syndrome." (PMID 27364742, 2016). "Additionally, alterations in critical signals regulating neurogenesis, such as presenilin-1, Notch 1, soluble amyloid precursor protein, CREB, and β-catenin underlie dysfunctional neurogenesis in Alzheimer's disease." (PMID 27199641, 2016). "BDNF may be an indirect target of Notch1 in a research of Alzheimer’s disease." (PMID 39090706, 2024). "It has been suggested that Notch1 participates in olfactory function, which is impaired in patients with Alzheimer disease (AD) and in experimental models of familial AD secondary to presenilin mutations." (PMID 31024234, 2019). "It is possible that H2O2 may increase Notch1 activation via γ-secretase activation, as H2O2-mediated increase in γ-secretase activation has been demonstrated in the pathogenesis of Alzheimer disease." (PMID 23597145, 2013).
ischemia (19 papers, 2012 to 2025). A hypoperfusion of the BLOOD through an organ or tissue caused by a PATHOLOGIC CONSTRICTION or obstruction of its BLOOD VESSELS, or an absence of BLOOD CIRCULATION. "Our findings indicate that the Xist/miR-32-5p/Notch-1 axis may be a novel molecular target for endogenous repair in ischemia-associated CNS diseases." (PMID 32850853, 2020). "The study by Pei and coworkers firstly showed that activation of endogenous Notch1 is critical to promote cardiomyocyte survival and sustain cardiac function after ischemia-reperfusion injury." (PMID 29636838, 2018). "Our previous study also demonstrated that activation of Notch1 signaling inhibited ROS production in hepatic ischemia/reperfusion (I/R) injury and MI/R injury." (PMID 27057278, 2016). "The three hub genes, STAT3, NOTCH1, and FOXO3, which are crucial essential factors to regulate the vascular diseases, and closely associated with modulation of proliferation, migration, differentiation and ischemia in a wide range of vascular diseases." (PMID 34988135, 2021). "Notch-1 and Dll-1 expression followed ischemia-induced miR-24-3p changes in the muscular microvascular cells, but not in the whole muscles, suggesting that endogenous modulation of miR-24-3p impacts on the regulation of alternative molecular pathways in the non-vascular component of the muscle." (PMID 32138369, 2020). "Our findings revealed that JNK could be phosphorylated by Notch-1 to induce the active caspase-3 and neuronal injury when intracerebral hemorrhage or ischemia occurred." (PMID 27655677, 2016). "In conclusion, our data identified that JNK could be phosphorylated by Notch-1 to induce the active caspase-3 and neuronal injury when intracerebral hemorrhage or ischemia occurred." (PMID 27655677, 2016). "EA pretreatment significantly enhanced Notch1, Notch4 and Jag1 gene transcriptions in the striatum, except Notch1 intracellular domain level, which could be increased evidently by ischemia." (PMID 22989188, 2012). "Here, we hypothesize that CMS aggrandized ischemia-related apoptosis injury and worsened synaptic integrity via gamma secretase-meditated Notch1 signaling." (PMID 22912748, 2012). "The immunofluorescence of Notch-1, NICD, RBP-JK, Hes-1 in activated microglia around the peri-ischemia cortex in I/R rats and NS rats was noticeably enhanced." (PMID 28288585, 2017). "In conclusion, this work suggested Notch-1 activates JNK pathway to induce the active caspase-3, leading to neuronal injury when intracerebral hemorrhage or ischemia occurred." (PMID 27655677, 2016). "The protein expression of Notch-1, NICD, RBP-JK and Hes-1 in the brain tissue of MCAO rats was also augmented following ischemia and was also attenuated with scutellarin treatment at 1 and 3 days." (PMID 25600517, 2015). "Indeed, HS can suppress Notch signaling as manifested by the decreased protein expression of Notch-1, NICD, RBP-JK and Hes-1 in peri-ischemia area and OGD activated BV-2 cells." (PMID 28288585, 2017). "Furthermore, in langendorff isolated heart perfusion model, we demonstrated that activation of Notch1 not only reduced the release of LDH and limited the infarct size, but also improved cardiac function after ischemia." (PMID 24098939, 2013).
Obesity (19 papers, 2016 to 2025). Accumulation of substantial excess body fat. "We proposed that the decreased expression level of Notch1 was the primary molecular mechanism underlying the physiological function of Slc35d3 in regulating obesity in mice." (PMID 37996411, 2023). "Our findings revealed a novel protective effect of TGFBI deficiency in obesity that is realized via the activation of the Notch-1 signaling pathway." (PMID 36854775, 2023). "To investigate whether Notch1 haploinsufficiency is associated with obesity, we fed 4-week-old male Notch1 heterozygous-deficient (N1+/−) mice and their WT counterparts high-fat high-sucrose (HF/HS) or normal diet, respectively, and measured body weight and daily food intake for 12 weeks." (PMID 34408185, 2021). "It has been suggested that the neurogenic locus notch homolog protein 1 (NOTCH1) signalling pathway contributes to the activation of mitochondrial glucose oxidation in obesity." (PMID 38988822, 2024). "We previously found that constitutive activation of Notch1 signaling in the PVAT phenocopied the effects of diet-induced obesity." (PMID 37895313, 2023). "In SAKI mice, Notch1 signaling was suppressed by overexpressed Slc35d3, which was correlated with the protective efficacy against obesity." (PMID 37996411, 2023). "In conclusion, we identify that SLC35D3 is involved in obesity by interacting with the NOTCH1 extracellular domain and promoting the accumulation of NOTCH1 in the ER, which can lead to the inhibition of NOTCH1 signaling." (PMID 37996411, 2023). "In this study, we show that SLC35D3 regulates white adipose tissue browning and obesity via NOTCH1 signaling." (PMID 37996411, 2023). "As expected, knockdown of Notch1 resulted in resistance to obesity as well as improved metabolism, which was more pronounced in Slc35d3 knockout mice." (PMID 37996411, 2023). "This suggests the involvement of Notch1 signal activity in the stemness of ADSCs, and that modulation of Notch1 signaling in ADSCs is a potentially useful therapeutic target in obesity." (PMID 34408185, 2021). "In conclusion, we demonstrated in the present study that haploinsufficiency of Notch1 promotes adipose tissue accumulation and modulates adipogenic signaling, resulting in obesity-induced insulin resistance." (PMID 34408185, 2021). "Interestingly, both ZOSV and ZOV showed improvement in DD and suppressed Notch-1 expression, suggesting that the beneficial effects of sac/val and val in the ZO model of obesity-associated DD may be, in part, explained by suppression of Notch-1 in fibroblasts and immune cells." (PMID 33882908, 2021). "Importantly, we identified that the CEBPB-LAP places itself upstream of Notch1 and DEPTOR signaling nodes which are additionally implicated in obesity and adipogenesis." (PMID 41282072, 2025). "This study aims to investigate the potential of EGCG in inhibiting Notch1 expression, promoting adipocyte browning, and improving obesity through the establishment of a molecular docking model, conducting molecular dynamics experiments, and utilizing in vitro cell models." (PMID 38893431, 2024). "Notch1, as an inflammatory marker protein, exerts regulatory effects on obesity development." (PMID 38893431, 2024). "Moreover, inhibiting Notch1 expression has been shown to significantly enhance brown fat thermogenesis, promote white fat browning, and ameliorate obesity." (PMID 38893431, 2024). "Although EGCG can improve inflammation by inhibiting Notch1 and has significant effects on obesity, it is still uncertain whether EGCG in adipose tissue can have the same metabolic-promoting and obesity-improving effects by targeting Notch1." (PMID 38893431, 2024). "In addition, knockdown of Notch1 shows considerable improvement in obesity and glucose and lipid metabolism, which is more pronounced in Slc35d3 knockout mice." (PMID 37996411, 2023).